SNAP25 (synaptosome associated protein 25)
Diseases named in the same sentence as SNAP25 in open-access papers (continued):
Sharing a sentence is not in itself a finding about the gene and the disease.
glioma (continued). "After we found a lower expression of SNAP25 in glioma, we explored its functional effects on glioma cells." (PMID 34490096, 2021). "The effect of SNAP25 on cell proliferation, migration and invasion was also examined, and the results exhibited that SNAP25 overexpression effectively inhibited cell proliferation, migration, invasion and dendritic formation, and promoted cell glutaminolysis of glioma cells." (PMID 34490096, 2021). "In the present study, we first identified the expression of SNAP25 in the glioma tissues and cells." (PMID 34490096, 2021). "In summary, these results demonstrated that SNAP25 could significantly inhibit glioma cell proliferation in vitro and sponge tumor growth in vivo." (PMID 34490096, 2021). "We hypothesized that SNAP25 could regulate GLS-mediated glutamine metabolism to inhibit glioma progression." (PMID 34490096, 2021). "Subsequently, we examined the role of SNAP25 in glioma migration and invasion." (PMID 34490096, 2021). "Also, SNAP25-knockdown glioma cells (A172 sh-SNAP25 and U118 sh-SNAP25) showed lower GLS expression compared to sh-NC cells and overexpression of SNAP25 witnessed an increased expression of GLS according to the western blot assay (p<0.05)." (PMID 34490096, 2021). "SNAP25, a tumor suppressor inhibited carcinogenesis of glioma via limiting glutamate metabolism by regulating GLS expression, as well as inhibiting dendritic formation, which could be considered as a novel molecular therapeutic target for glioma." (PMID 34490096, 2021). "Then xenograft model of glioma in vivo indicated a time-dependent aggressive growth of the xenograft in rat brains and SNAP25 acted as an efficient tumor suppressor as U87Mcherry Lv-SNAP25 rats showed lower growth rate, less weight-loss and longer survival time than U87Mcherry Lv-NC animals." (PMID 34490096, 2021). "SNAP25 was decreased in level of expression in glioma cells, especially in U118 and A172 cells." (PMID 34490096, 2021). "SNAP25 is a member of the SNARE family, associated with severe synaptopathies like Schizophrenia and also proteinopathies like Alzheimer’s disease but its function in glioma is seldom studied." (PMID 34490096, 2021). "In this study, SNAP25 was mined to have significantly lower expression levels in glioma from the mRNAs expression profiles in TCGA dataset and lower-expressed SNAP25 indicated an unfavorable prognosis of glioma patients." (PMID 34490096, 2021). "Then the lower expression of SNAP25 in glioma tissues and cell lines was validated." (PMID 34490096, 2021). "Also, the relationship between SNAP25 and MAP2 was not well distinguished as the low expression of MAP2 in U87Mcherry Lv-SNAP25 glioma cell-transplanted-xenograft may be simply related to the lack of tumor growth and size." (PMID 34490096, 2021). "However, the specific mechanism and prognostic value of SNAP25 during glioma progression remain unclear." (PMID 34490096, 2021). "The proliferation, migration, and invasion assays proved that knockdown of GLS accelerated the proliferation, migration and invasion rate of glioma parental cells, and downregulation of GLS in SNAP25-overexpressesd glioma cells could rescue the tumor-suppressive function of SNAP25 in glioma cells." (PMID 34490096, 2021). "But the further mechanism of how SNAP25 regulates glioma progression remains unknown." (PMID 34490096, 2021). "In general, SNAP25 overexpression inhibited cell migration and invasion of U118 and A172 cells, and SNAP25 knockdown promoted cell migration and invasion of glioma cells, and upregulation of SNAP25 could also inhibit the dendritic formation of the tumor in vivo." (PMID 34490096, 2021). "Since SNAP25 basically functions as a critical role in synaptic activity regulating vesicle transfer between neighboring cells in the nervous system, SNAP25 was hypothesized to play a neuron-glioma cell interaction-activated role which can influence brain cancer growth." (PMID 34490096, 2021).
glioma (continued). "To further prove that SNAP25 inhibited glioma progression through activating GLS, we applied GLS-shRNA to rescue the SNAP25 overexpressed cells." (PMID 34490096, 2021). "SNAP25 could regulate glutaminase (GLS)-mediated glutaminolysis, and GLS knockdown could rescue the anti-tumor effect of SNAP25 in glioma cells." (PMID 34490096, 2021). "First, we detected the expression of SNAP25 in glioma cell lines (U87, U251, U118, and A172), when compared to normal human astrocytes (NHAs) by RT-qPCR and western blot assays." (PMID 34490096, 2021). "But the exact role of GLS in SNAP25-regulated glioma progression has not been studied." (PMID 34490096, 2021). "Next, the CGGA dataset was selected to show a negative correlation between the expression of SNAP25 and the WHO grades of glioma." (PMID 34490096, 2021).
colon cancer (6 papers, 2014 to 2025). "The core gene in the PPI network SNAP25, associated with the microenvironment and immune response, has been identified as a predictor of poor outcomes in colon cancer." (PMID 40170839, 2025). "Based on the TIMER database, SNAP25 was closely associated with tumor-infiltrating immune cells in a variety of cancer types, including colon cancer, hepatocellular liver cancer, lung squamous cell carcinoma, testicular cancer, and PCa." (PMID 35392903, 2022). "In recent years, a growing number of studies have identified an association between SNAP25 levels and gastric cancer, colon cancer, hepatocellular carcinoma, lung cancer, and papillary thyroid cancer." (PMID 35392903, 2022). "This suggested that immunity and metabolism may be as well involved in the underlying mechanism of SNAP25 in colon cancer." (PMID 33150073, 2020). "Those may bring novel insights into the potential underlying mechanism of SNAP25 in colon cancer." (PMID 33150073, 2020). "Therefore, SNAP25 is extremely closely associated with various types of TILs, and has the potential to serve as a prognosis biomarker and an immunotherapeutic target for colon cancer." (PMID 33150073, 2020). "Bioinformatic analysis suggests that SNAP25 is involved in cancer-related signaling pathway, immunity and metabolism processes, which may provide a new target for investigating the underling mechanism of colon cancer." (PMID 33150073, 2020). "It was reported that SNAP25 was overexpressed in colon cancer samples, and abnormal expression of SNAP25 indicated a poor prognosis of colon cancer patients." (PMID 34490096, 2021). "qRT-PCR results revealed that AQP4 and SNAP25 were significantly elevated in colon cancer tissues compared with adjacent normal tissues (P = 0.003, 0.001)." (PMID 33150073, 2020). "One major limitation is that the present research was mainly based on previous data from TCGA and GEO, therefore, future investigations in vivo and vitro are needed to investigate the effect of SNAP25 in colon cancer." (PMID 33150073, 2020). "SNAP25 is a microenvironment-related and immune-related gene that can predict poor outcomes in colon cancer." (PMID 33150073, 2020). "In summary, SNAP25 is a microenvironment-related and immune-related gene that can predict poor outcomes in colon cancer." (PMID 33150073, 2020). "Interestingly, the mRNA relative expression levels of both AQP4 and SNAP25 were significantly elevated in colon cancer tissues compared with adjacent normal tissues (P = 0.003, 0.001)." (PMID 33150073, 2020). "Next, we investigated the underlying mechanism of AQP4 and SNAP25 in colon cancer by GSEA, and found that the high expression of SNAP25 might be involved in cancer-related signaling pathway, immunity and metabolism processes." (PMID 33150073, 2020). "A recent study indicated that SNAP25 was a microenvironment-related gene that predicted poor outcomes in colon cancer, and gene set enrichment analysis (GSEA) suggested that SNAP25 was involved in metabolism progress." (PMID 34490096, 2021). "Although the clinical significances and functions of SNAP25 for colon cancer have not been previously reported, it may serve as prognosis biomarker according to this study." (PMID 33150073, 2020).
hippocampal atrophy (6 papers, 2018 to 2024). "Taken together, future evaluation of the associations of CSF VAMP-2 and SNAP-25 with in vivo neural correlates (e.g. hippocampal atrophy) of declining episodic memory and other cognitive functions in AD patients as measured with structural MRI, could provide valuable information." (PMID 37898760, 2023). "In this study, to further confirm our previous findings that reduced synaptic proteins in EVs are associated with the development of AD, we examined the relationship between concentrations of SNAP25, GAP43, neurogranin, and synaptotagmin 1 and degrees of hippocampal atrophy in patients with AD." (PMID 38528511, 2024).
Intellectual disability (6 papers, 2016 to 2023). "In 2013, the first pathogenic variant in the SNAP25 gene was reported, caused by a missense mutation, V48F, in a patient presenting with severe encephalopathy, intellectual disability and generalized epilepsy that is resistant to antiepileptic (AED) treatment." (PMID 37066095, 2023). "The patients harboring pathogenic SNAP25 variants commonly present with a wide array of neurological symptoms including seizures, various degrees of intellectual disability, muscle weakness, speech delays, and cerebellar ataxia." (PMID 37066095, 2023). "SNAP25-related CMS has been reported only in a single female who presented with myasthenia, congenital contractures, cortical hyperexcitability, cerebellar ataxia, and severe intellectual disability." (PMID 30808424, 2019).
Obesity (6 papers, 2021 to 2023). Accumulation of substantial excess body fat. "In mouse models of obesity, SNAP25 was identified as a major target gene of miR-342-3p and the reduced expression of SNAP25 may link to functional impairment hypothalamic neurons and excess of food intake." (PMID 36704034, 2022). "Furthermore, consistent with this, it has been reported that low expression of the SNARE proteins STX1, SNAP25, and VAMP2 is associated with insulin secretory defects in rodents and humans with obesity and type 2 diabetes." (PMID 35804190, 2022).
prostate carcinoma (6 papers, 2016 to 2024). A carcinoma that arises from epithelial cells of the prostate gland. "In the marker genome, downregulation of SNAP25 was clearly involved in cancer pathways, prostate cancer, and the WNT, TGF-β, and MAPK signaling pathways." (PMID 35392903, 2022). "However, a recent study using TCGA database reported that SNAP25 expression correlates with tumour infiltration of immune cells in colon and prostate cancers." (PMID 38291183, 2024).
vascular dementia (6 papers, 2018 to 2025). A degenerative vascular disorder affecting the brain. "The expression level of SNAP25 in the hippocampus of rats with vascular dementia is closely related to the severity of disease." (PMID 34497527, 2021).
amyloid (5 papers, 2022 to 2025). "This is in contrast to other synaptic proteins measured in CSF, for example, GAP‐43, SNAP‐25, and neurogranin, which are changed only in response to amyloid pathology." (PMID 40522075, 2025). "Additionally, these results confirm that CSF SNAP-25 is increased in relation to amyloid pathology in the AD continuum." (PMID 35659284, 2022). "MW-151 treatment prevented loss of synapses, as measured by western blots for the levels of PSD-95, synaptophysin, syntaxin, and synaptosomal-associated protein 25 (SNAP25), without affecting amyloid plaque load or soluble Aβ concentrations." (PMID 35783099, 2022). "However, developing evidence suggests that SNAP-25, amongst other synaptic biomarkers, is specifically associated with amyloid pathology, as no change has been found in SNAP-25 levels in non-amyloid pathologies, such as in frontotemporal dementia (FTD)." (PMID 35659284, 2022).
Cerebral ischemia (5 papers, 2014 to 2022). Restriction of arterial blood supply to the brain associated with insufficient oxygenation to support the metabolic requirements of the tissue. "To examine the detrimental effect of ischemic damage on synaptic proteins following cerebral ischemia, we studied the expression of synaptophysin, and synaptosomal-associated protein-25 (SNAP-25)." (PMID 31798514, 2019). "The injured cortical tissues of rats with cerebral ischemia exhibited decreased protein expression of neuron-related MAP-2 and SNAP25, though there was evidence of the increased protein expression of macrophage/microglia-related CD68 and astrocyte-related GFAP." (PMID 34943061, 2021). "We semi-quantified the SNAP-25, GAP-43 and synaptophysin immunofluorescence since these indicators of synaptic structure have previously been used to evaluate neuroplasticity in other models of cerebral ischemia." (PMID 25259609, 2014).
epileptic encephalopathies (5 papers, 2022 to 2025). "It has been shown that Snap25 is a causative factor for developmental and epileptic encephalopathies of infancy and childhood." (PMID 39083243, 2025). "We studied three mutations in SNAP25 that cause epileptic encephalopathy: V48F, and D166Y in the synaptotagmin-1 (Syt1)-binding interface, and I67N, which destabilizes the SNARE complex." (PMID 38411501, 2024). "In fact, a recent article revealed aberrant spontaneous NT release with some mutations from SNAP25-associated encephalopathies, indicating that when this form of release is affected it could result in developmental and epileptic encephalopathies." (PMID 35193927, 2022). "Interestingly, 2 variants at Asp166 have been identified in individuals with SNAP25 developmental and epileptic encephalopathy." (PMID 35101335, 2022).
insulinoma (5 papers, 2013 to 2024). "This study examined the effect of collagen IV-β1-integrin on exocytotic proteins (Munc18-1, Snap25, and Vamp2) involved in insulin secretion using rat insulinoma (INS-1) cell line." (PMID 35573663, 2022). "It has been reported that insulinoma cells are refractory to BoNT/A binding; however, our highly sensitive cleaved-SNAP25 immunoassay does reveal some efficacy of botulinum-based targeting (Bitox)." (PMID 23638840, 2013). "The anatomical data were confirmed by qPCR detection of the three transcripts in both INS-1E [rat insulinoma; (ΔCT values: 15.2 (Gapdh), 20.6 (Stx4), 20.2 (Snap25), and 17.1 (Scgn)) and αTC1-6 cell lines (mouse adenoma; ΔCT values: 14.3 (Gapdh), 31.1 (Stx4), 17.9 (Snap25), and 28.0 (Scgn)]." (PMID 38593081, 2024). "Moreover, the phosphorylation of SNAP-25 at Ser187 by PKC was necessary for the enhancement of Ca2+-triggered exocytosis by phorbol ester in an insulinoma cell line, and the inhibition of SNAP-25 phosphorylation at Ser187 down-regulated morphine-induced SNARE complex formation in neurons." (PMID 28486561, 2017). "Next REST was overexpressed in the mouse insulinoma cell line MIN6 and gene expression was analysed by qPCR for Rest, Ins2, Pdx1, Snap25 and Scrt1 three days post infection." (PMID 33888791, 2021). "The SNAP25 protein, responsible for hormone secretion and located on the inner leaflet of the plasma membrane, can be visualized in five tested NET cells (pheochromocytoma PC12, insulinoma Min6, neuroblastomas SH-SY5Y and Neuro2A, and pituitary AtT-20)." (PMID 23638840, 2013).
memory impairment (5 papers, 2020 to 2024). "For example, the reduction of SNAP25 causes postsynaptic loss and learning and memory impairment." (PMID 34194312, 2021). "Moreover, melatonin reverses Aβ1–42‐induced neurotoxicity and memory impairment by increasing the levels of presynaptic proteins (Synaptophysin and SNAP25) and postsynaptic proteins (PSD95 and SNAP23)." (PMID 39500626, 2024). "Decrease in the rate or absence of SYN, SNAP-25, and SYT1 mRNAs ends to learning and memory impairment." (PMID 36588719, 2022).
Ataxia (4 papers, 2017 to 2026). Ataxia refers to impaired coordination of voluntary muscle movement. "Seven SNAP25 variants (NM_003081.4) have been reported to date in eight patients presenting with seizures, intellectual disability, speech delay, cerebellar ataxia, and muscle weakness." (PMID 39596051, 2024).
autism spectrum disorder (4 papers, 2017 to 2023). A spectrum of developmental disorders that includes autism, and Asperger syndrome. "The results of genetic studies suggest a possible role for SNAP-25 polymorphism in the development of autism spectrum disorders (ASDs); however, there are no data available on whether changes in SNAP-25 expression also affect animals in rodent models of ASD." (PMID 32367505, 2020).
Creutzfeldt-Jakob disease (4 papers, 2010 to 2025). "The formation of PrPSc is accompanied by a decreased expression of proteins involved in exocytosis and neurotransmission, such as synaptophysin, SNAP-25 and synapsins in the brains of scrapie-infected mice and in humans affected with Creutzfeldt-Jakob disease (CJD)." (PMID 20374666, 2010). "The levels of synaptic markers synaptosomal-associated protein 25 (SNAP-25) and neurogranin (Ng) have been shown to increase early in the cerebrospinal fluid (CSF) of patients with Creutzfeldt-Jakob disease (CJD) and to have prognostic potential." (PMID 37684653, 2023).
Down syndrome (4 papers, 2013 to 2025). "The pathogenic genome rate of fetal pleural effusion was 12.9% (4/31), including 2 cases of trisomy 21 syndrome, 1 case of large fragment deletion, and 1 case of a single-gene mutation (SNAP25 gene mutation)." (PMID 41401185, 2025). "Of these, transcript levels of Synaptosome Associated Protein 25 (SNAP25), a protein implicated in AD and Down syndrome (DS), were significantly down-regulated in Knight-C4, as it has been previously reported in AD." (PMID 38687811, 2024).
hypothyroidism (4 papers, 2014 to 2025). Abnormally low levels of thyroid hormone. "In conclusion, this study demonstrated that hypothyroidism induces alterations of hippocampal Ach level and AChE activity, as well as syt-1 and SNAP-25 expression, in adult rats." (PMID 25371181, 2015). "Using immunohistochemical analysis, the results indicated that the effects of adult-onset hypothyroidism on syt-1 and SNAP-25 are different, although these proteins are required for neurotransmitter exocytosis." (PMID 25371181, 2015). "By the administration of T4, it was observed that hypothyroidism-induced downregulation of the syt-1 protein and upregulation of the SNAP-25 protein was restored in the hippocampus." (PMID 25371181, 2015). "While SNAP-25 overexpression may be a compensatory mechanism against adult-onset hypothyroidism, functioning to rescue vesicle exocytosis." (PMID 25371181, 2015). "Therefore, in this study, we have investigated the concentration of ACh and the activity of AChE, as well as the expression levels of syt-1 and SNAP-25 in the hippocampus of adult-onset hypothyroidism." (PMID 25371181, 2015). "In addition, the concentrations of Ca2+/calmodulin-independent protein kinase (CaMKII), neurogranin, SNAP-25 and calmodulin, in which changes were induced by hypothyroidism, have been found to return to basal levels following T4 replacement therapy." (PMID 24520241, 2014). "A marked reduction in cholesterol biosynthesis was also observed in hypothyroidism by a decrease in the level of SREBP-2 and its regulated enzymes in the frontal cortex, whereas changes in the expression of SNAP-25 and GLP-1 and 2 receptors indicate a weakening of neuroprotective mechanisms." (PMID 35951260, 2022). "Significantly, co-administration of T4 and DON led to normalization of the syt-1 and SNAP-25 levels, suggesting that DON treatment may facilitate the recovery of synaptic protein impairment induced by hypothyroidism." (PMID 25371181, 2015).